MIR454 (microRNA 454)
Synonyms: hsa-mir-454; MIRN454; mir-454
Gene: MicroRNA gene on chromosome 17 (59,137,758 to 59,137,872, reverse strand). Ensembl gene ENSG00000211514.
Gene Ontology:
Biological process: miRNA-mediated post-transcriptional gene silencing
Cellular component: RISC complex
Homologues: Orthologues: chimpanzee ptr-mir-454 (100% identical), macaque mml-mir-454 (99% identical), zebrafish mir454a (66% identical), dog MIR454 (59% identical), pig MIR454 (59% identical), tropical clawed frog xtr-mir-454 (53% identical).